NPHS1 (NPHS1 adhesion molecule, nephrin)
Description:
Seems to play a role in the development or function of the kidney glomerular filtration barrier. Regulates glomerular vascular permeability. May anchor the podocyte slit diaphragm to the actin cytoskeleton. Plays a role in skeletal muscle formation through regulation of myoblast fusion (By similarity).
Synonyms: NPHN; CNF; nephrin
Tractability: Antibody: UniProt places it where antibodies can reach, with high confidence; its Gene Ontology location is reachable by antibodies, with high confidence; UniProt predicts a signal peptide or a membrane-spanning region.
Gene: Protein-coding gene on chromosome 19 (35,825,372 to 35,869,287, reverse strand). Ensembl gene ENSG00000161270.
Subcellular location: Cell membrane
Pathways (Reactome):
Cell-Cell communication: Nephrin family interactions
Gene Ontology:
Molecular function: myosin binding; protein binding; cell adhesion molecule binding
Biological process: glomerular basement membrane development; podocyte development; protein localization to synapse; cell-cell adhesion; slit diaphragm assembly; myoblast fusion; skeletal muscle tissue development
Cellular component: extracellular exosome; plasma membrane; cell-cell junction; slit diaphragm; cell periphery; focal adhesion
Genetic constraint (gnomAD): Loss-of-function variants: 106 observed, 143.02 expected, observed/expected ratio (o/e) 0.74, 90% interval 0.63 to 0.87. The upper end of that interval is the gene's LOEUF score, 0.87, which puts it in group 3 of 6, group 1 being the genes least tolerant of losing a copy. Missense variants: 1,577 observed, 1,692.2 expected, observed/expected ratio (o/e) 0.93, 90% interval 0.89 to 0.97. Synonymous variants: 705 observed, 712.41 expected, observed/expected ratio (o/e) 0.99, 90% interval 0.93 to 1.05.
Gene-disease validity (ClinGen):
ClinGen rates the evidence that NPHS1 causes each of these diseases.
congenital nephrotic syndrome, Finnish type (autosomal recessive): Definitive. Congenital nephrotic syndrome, Finnish type is characterized by protein loss beginning during fetal life.
Homologues: Orthologues: chimpanzee NPHS1 (99% identical), macaque NPHS1 (94% identical), dog NPHS1 (87% identical), pig NPHS1 (86% identical), rabbit NPHS1 (85% identical), guinea pig NPHS1 (83% identical), mouse Nphs1 (81% identical), rat Nphs1 (81% identical), tropical clawed frog nphs1 (43% identical), zebrafish nphs1 (38% identical), Drosophila melanogaster sns (28% identical), Drosophila melanogaster hbs (26% identical). Paralogues in human: KIRREL3 (14% identical), KIRREL1 (14% identical), KIRREL2 (13% identical).
Diseases named in the same sentence as NPHS1 in open-access papers:
NPHS1 is named in the same sentence as 79 diseases in open-access papers, as found by Europe PMC text mining. Sharing a sentence is not in itself a finding about the gene and the disease. The quoted sentences say what the papers report.
congenital nephrotic syndrome (47 papers, 2007 to 2025). "Three genes were associated with congenital nephrotic syndrome: NPHS1 (2/2 families), LAMB2 (1/1 family) and COL4 A3 (1/1 family)." (PMID 40402239, 2025). "Most of the genes commonly associated with congenital nephrotic syndrome have reported ocular manifestations (NPHS1, NPHS2, WT1, LAMB2, PAX2, PLCE1)." (PMID 37578539, 2024). "Congenital nephrotic syndrome of the Finnish type (CNF) (MIM# 256300) is caused by biallelic variants in the gene NPHS1, encoding nephrin, an integral component of the kidney filtration barrier." (PMID 38987283, 2024). "Individuals with biallelic pathogenic variants in NPHS1 develop congenital nephrotic syndrome of the Finnish type (CNF), also referred to as congenital nephrotic syndrome type 13." (PMID 38987283, 2024). "Participant NE033 received a diagnosis of severe congenital nephrotic syndrome (Finnish type), harbouring a homozygous variant in the NPHS1 gene (c.1379G > A, p.Arg460Gln)." (PMID 38028619, 2023). "Pathogenic variants in NPHS1 were also seen in 16 cases, especially in infants with congenital nephrotic syndrome (CNS)." (PMID 37204080, 2023). "Nephrin gene mutation in congenital nephrotic syndrome (NPHS1) in a mouse model was detected by inactivating NPHS1 in embryonic stem cells by homologous recombination." (PMID 35130988, 2022). "NEPHRIN, encoded by the NPHS1 gene, is crucial for the formation of the slit diaphragm, and mutations in NPHS1 cause congenital nephrotic syndrome of the Finnish type (CNF), an autosomal recessive steroid-resistant nephrotic syndrome." (PMID 36187478, 2022). "The human gene encoding Nephrin, NPHS1, is mutated in congenital nephrotic syndrome, a lethal kidney disease." (PMID 35356892, 2022). "The mutation and polymorphism of nephrin gene NPHS1 impact the development of congenital nephrotic syndrome of Finnish type (CNF), MCNS, and other diseases as well as the occurrence of its proteinuria." (PMID 35265098, 2021). "NPHS1 encodes nephrin, a type-1 transmembrane protein found at the podocyte slit diaphragm, and mutations in this gene are responsible for most cases of congenital nephrotic syndrome (CNS)." (PMID 34031708, 2021). "Abnormalities of nephrin caused by mutations in the NPHS1 gene have been implicated in the autosomal recessive congenital nephrotic syndrome in a Finnish population." (PMID 34576149, 2021). "Among the recruited patients with congenital nephrotic syndrome caused by NPHS1 mutations, we focused on two patients in this study." (PMID 33597637, 2021). "Glomerular chips generated from iPSCs from a patient with congenital nephrotic syndrome (mutation NPHS1 mutation) displayed reduced level of podocin and nephrin." (PMID 32118002, 2020). "Since 1998, when mutations within the gene NPHS1 were identified to cause congenital nephrotic syndrome of the Finnish type, SRNS has been largely attributed to genetic mutations that lead to impaired function of the glomerular filtration barrier." (PMID 32708597, 2020). "Initially, Kestilä described NPHS1 as the pathogenic gene of the congenital nephrotic syndrome of the Finnish type (CNF)." (PMID 31216994, 2019). "The first gene identified was the nephrin gene (NPHS1), whose mutations cause Finnish-type congenital nephrotic syndrome (CNS)." (PMID 28752288, 2018). "NPHS1 was first identified in 1998 as the causative gene in congenital nephrotic syndrome (CNS) of the Finnish-type, which is inherited in an autosomal recessive manner." (PMID 30212551, 2018). "Mutations in the Nphs1 gene encoding nephrin protein lead to congenital nephrotic syndrome characterized by absence or profound impairment of the slit diaphragm and manifesting as severe proteinuria or nephrotic syndrome." (PMID 28286744, 2017). "Nephrin—the product of the NPHS1 gene—was discovered when mutations in NPHS1 were found in patients with congenital nephrotic syndrome of the Finnish type." (PMID 24327929, 2013).
congenital nephrotic syndrome (continued). "Phenotypic heterogeneity also exists for nephrin (NPHS1) mutations which have been reported to result in congenital nephrotic syndrome, steroid-resistant MCD and FSGS." (PMID 23663351, 2013). "Nephrin is encoded by NPHS1, the gene mutated in Congenital Nephrotic Syndrome of the Finnish variety, a disorder characterized by massive proteinuria and nephrosis." (PMID 23226445, 2012). "A mutation of NPHS1, encoding nephrin and responsible for the Finnish-type congenital nephrotic syndrome, is found in most patients presenting with a nephrotic syndrome in the first 3 months of life." (PMID 21904676, 2011). "Mutations of the nephrin gene, NPHS1, produce congenital nephrotic syndrome of the Finnish type (CNF)." (PMID 21808734, 2011). "Nephrin (encoded by NPHS1) is a transmembrane protein expressed in podocytes and its mutations cause severe congenital nephrotic syndrome and renal failure known as Finnish type nephrotic syndrome." (PMID 22013520, 2011). "The gene mutated for congenital nephrotic syndrome, nephrin (NPHS1) is localized to the slit diaphragm of the podocyte and is tightly associated with CD2-associated protein (CD2AP)." (PMID 17647026, 2007). "The discovery of the NPHS1 gene mutation in congenital nephrotic syndrome of the Finnish type over 25 years ago, which encodes the transmembrane protein nephrin, has since revolutionized our understanding of the glomerular filtration barrier at a molecular level." (PMID 40136474, 2025). "Digenic inheritance has also already been reported to have a prognostic role in other kidney diseases, such as congenital nephrotic syndrome (mutations in NPHS1 and NPHS2), autosomal dominant polycystic kidney disease (mutations in PKD1 and PKD2) and Bartter's syndrome." (PMID 33330536, 2020). "Human mutations in the NPHS1 gene, which encodes nephrin, are associated with congenital nephrotic syndrome of the Finnish type; alterations in expression, location, or phosphorylation status of nephrin have been observed in human glomerular diseases and animal podocyte-injury models." (PMID 28880939, 2017). "Congenital nephrotic syndrome is an inherited disorder caused by mutations in the NPHS1 gene." (PMID 28392951, 2017). "Currently, three genes are associated with congenital nephrotic syndrome: NPHS1, NPHS2, and WT1." (PMID 21904677, 2011). "NPHS1 mutations were detected in 36 of 86 (42%) families with congenital nephrotic syndrome." (PMID 19165332, 2009). "It is significantly more prevalent in the Finnish population, where Finnish-type Congenital Nephrotic Syndrome (CNF) occurs in approximately 1 in 8,200 live births, with NPHS1 (19q13.1) gene variants accounting for 98% of cases." (PMID 41163923, 2025). "Second, we detected three congenital nephrotic syndrome (CNS) gene variants, NPHS2 (five cases), NPHS1 (two cases), and WT1 (one case) in eight patients with a mean age of 52 months." (PMID 39625990, 2024). "Mutations of NPHS1, encoding NEPHRIN, a podocyte protein essential for normal GFB, cause congenital nephrotic syndrome (CNS) of the Finnish type (CNF), which accounts for about 50% of CNS cases." (PMID 36187478, 2022). "Mutations in the NPHS1 gene, which encodes NEPHRIN, cause congenital nephrotic syndrome, resulting from impaired slit diaphragm (SD) formation in glomerular podocytes." (PMID 33597637, 2021). "NPHS1, that relates to congenital nephrotic syndrome (CNS) and SRNS, is one of the most frequently reported genes." (PMID 31216994, 2019). "The best characterized inherited nephrotic syndromes are congenital nephrotic syndrome of the Finnish type (CNF) and Steroid Resistant Nephrotic Syndrome (SRNS), due to mutations in NPHS1 and NPHS2 genes, respectively." (PMID 21904677, 2011). "Mutations in NPHS1 can lead to congenital nephrotic syndrome, characterized by proteinuria and absence of slit diaphragms." (PMID 41368354, 2025).
congenital nephrotic syndrome (continued). "NPHS1 (OMIM 602716) encodes nephrin, an immunoglobulin protein, which represents the hallmark of genetic NS/FSGS, being the first recessive gene discovered to be causative for congenital nephrotic syndrome (CNS) in the Finnish population in 1998." (PMID 37728640, 2024). "Given the critical role that nephrin plays in maintenance of the SD, it is not surprising that mutations affecting the nephrin gene, NPHS1, are associated with the severe kidney disease congenital nephrotic syndrome of the Finnish type." (PMID 32708597, 2020).
nephrotic syndrome (46 papers, 2009 to 2025). A collection of symptoms that include severe edema, proteinuria, and hypoalbuminemia; it is indicative of renal dysfunction. "Congenital nephrotic syndrome is a rare autosomal recessive genetic disorder, with the Finnish type caused by NPHS1 variants being the most common." (PMID 41163923, 2025). "Nephrotic syndrome can manifest as a monogenic disease caused by deleterious variants in genes such as NPHS1, which encodes nephrin." (PMID 40085383, 2025). "Initially unexpected, it was found that the recurrence of nephrotic syndrome after transplantation in patients with congenital nephrotic syndrome of Finnish-type was caused by the development of antibodies against the donor NPHS1 genotype." (PMID 39125467, 2024). "CNS was first identified within Finnish populations, hence the name “Finnish type nephrotic syndrome”, which is commonly associated with NPHS1 mutations." (PMID 39596340, 2024). "Although heterozygous allele carrying parents or siblings of patients affected by CNF are generally regarded as healthy, evidence for heterozygous NPHS1 variants in humans being associated with nephrotic syndrome is emerging." (PMID 38987283, 2024). "Antibody production can explain the pathogenesis of post-transplantation nephrotic syndrome in NPHS1-associated NS, which is most accurately considered as ‘anti-nephrin’ antibody disease rather than true disease recurrence." (PMID 34031708, 2021). "In this multicenter study, the clinical manifestations and features of NPHS1 variants in Chinese children with nephrotic syndrome were researched." (PMID 34859019, 2021). "The results of the current study and previous findings confirm that NPHS1 variants can cause a broader variety of clinical phenotypes in nephrotic syndrome including childhood- and adult-onset focal segmental glomerulosclerosis than CNS." (PMID 34859019, 2021). "Especially in individuals presenting with FSGS or nephrotic syndrome before or at the age of 18 years old, the most common genes in which a mutation was found continues to be limited to only a few genes, including NPHS1 and NPHS2." (PMID 31216994, 2019). "A congenital nephrotic syndrome patient with NPHS1 mutation was also reported to respond partially to steroids and cyclosporine A therapy." (PMID 29594119, 2018). "An example is NPHS1 mutation, that is causative of one of the most clinically relevant forms of congenital nephrotic syndrome." (PMID 29942802, 2018). "Their results showed that misfolding and defective intracellular transport was the most common cause in development of the nephrotic syndrome in patients carrying missense mutations in NPHS1." (PMID 28392951, 2017). "The patients with genetic mutation of NPHS1 present with Finnish-type congenital nephrotic syndrome." (PMID 27088082, 2016). "Nephrotic syndrome of the Finnish type (OMIM #256300) is a genetic disorder caused by homozygous or compound heterozygous mutations in the gene NPHS1 encoding for the SD protein nephrin." (PMID 25126087, 2014). "These include mutations in the NPHS1 gene encoding the slit diaphragm component, nephrin, which causes congenital nephrotic syndrome of the Finnish type and results in massive proteinuria at birth." (PMID 21915268, 2011). "Moreover, NPHS1 is a susceptibility gene for steroid-sensitive nephrotic syndrome in patients from East Asian populations." (PMID 40085383, 2025). "Abnormalities of glomerular podocytes can be recapitulated in kidney organoids from iPSCs obtained from a patient with congenital nephrotic syndrome of the Finnish type: mutations in the NPHS1 gene, which encodes nephrin, lead to the impaired formation of the slit diaphragm in glomerular podocytes." (PMID 40777107, 2024). "NPHS1 encodes a member of the immunoglobulin family of cell adhesion molecules that functions in the glomerular filtration barrier in the kidney, and its mutations are associated with nephrotic syndrome." (PMID 37435641, 2024).
nephrotic syndrome (continued). "Finally, highly penetrant pathogenic variants in NPHS1 are known causes of monogenic nephrotic syndrome." (PMID 37868272, 2023). "Likewise, genetic correction of the single amino acid mutation of iPSCs generated from a congenital nephrotic syndrome patient due to NPHS1 mutations has restored nephrin localization and phosphorylation and slit diaphragm formation." (PMID 32586408, 2020). "Moreover, the authors found that in nephrotic syndrome due to NPHS1 mutations, nephrin deficiency activates the intrinsic NF-κB pathway in podocytes promoting podocyte injury." (PMID 31095586, 2019). "NPHS1 mutations are the most common cause of congenital nephrotic syndrome worldwide." (PMID 29594119, 2018). "In addition, 3D organoid glomeruli from a congenital nephrotic syndrome patient with compound heterozygous NPHS1 mutations reveal reduced protein levels of both NEPHRIN and PODOCIN." (PMID 30514835, 2018). "Similarly, genetic correction of the single amino acid mutation of iPSCs generated from a congenital nephrotic syndrome patient containing NPHS1 mutations has restored nephrin localization and phosphorylation, colocalization with NEPH1 and podocin, and slit diaphragm formation." (PMID 30865165, 2019). "Three cases of NPHS1 mutation in children with nephrotic syndrome responsive to steroids and cyclosporine have been described, suggesting that hypomorphic mutations (such as those here reported) may coexist with the more frequent and severe clinical phenotypes." (PMID 29942802, 2018). "Likewise, NPHS1 mutations are associated with nephrotic syndromes and the authors speculate that this mutation could modify the Alport Syndrome phenotype underlain by the COL4A5 mutation." (PMID 26179878, 2015). "Genetic variants in NPHS1, NPHS2, and CD2AP demonstrate the strongest causal link to human nephrotic syndromes, reflecting their indispensable structural and signaling functions." (PMID 41368354, 2025). "Mutations on either NPHS1 or NPHS2 lead to the malfunctioning of the slit diaphragm, causing podocyte collapse, alteration in glomerular permeability, and, hence, nephrotic syndrome’s main feature such as proteinuria." (PMID 39596340, 2024). "Any faults in NPHS1 disrupt this important role, hence leading to proteinuria, which characterizes nephrotic syndrome." (PMID 39596340, 2024). "We reported a dichorionic diamniotic placental twin (DD twin) with a family history of a congenital nephrotic syndrome of the Finnish type (CNF), of which the parent had heterozygous for the NPHS1 gene mutation." (PMID 37101999, 2023). "One study of patients with NPHS1 Finnish-type CNS demonstrated post-transplantation nephrotic syndrome in 25% with a mean time to disease onset of 12 months." (PMID 34031708, 2021). "To overcome this limitation, we generated a novel, inducible, podocyte-specific transgenic mouse model (Epb41l5fl/fl*Nphs1-rtTA-3G*tetOCre), developing nephrotic syndrome in adult mice." (PMID 34203913, 2021). "Mutations in the NPHS1, NPHS2, LAMB2, and the WT1 genes are responsible for causing nephrotic syndrome (NS) in two third of the early onset cases." (PMID 30013592, 2018). "The mutations of NPHS1 and NPHS2 cause nephrotic syndrome resistant to immunotherapy and show less recurrence after renal transplantation." (PMID 27088082, 2016). "The commonest genes associated with nephrotic syndrome differ at birth (NPHS1, NPHS2, WT1, LAMB2, PAX2, PLCE1), in childhood or adolescence (NPHS1, NPHS2, WT1, LAMB2, SMARCAL1, NUP107, TRPC6, PLCE1) and in adults (COL4A3-COL4A5, GLA, ACTN4, CD2AP, INF2, TRPC6)." (PMID 37578539, 2024). "Notably, within this population, genes associated with nephrotic syndromes include MYOE1, NPHS1, NPHS2, and PLCE." (PMID 39519211, 2024). "Biallelic pathogenic variants in NPHS1 leading to a complete absence of nephrin were the most commonly reported and best understood instance of nephrotic syndrome occurring post-transplantation." (PMID 34031708, 2021).
nephrotic syndrome (continued). "For example, mutations of podocyte-associated genes account for approximately 30% of pediatric cases of steroid-resistant nephrotic syndrome with one of the four genes (NPHS1, NPHS2, WT1, and LAMB2) identified in 66% of nephrotic syndrome manifesting within the first year of life." (PMID 31049720, 2020). "When compared with monogenic mutations sharing a common nephrotic syndrome phenotype, the RCAD146 classifier also identified subjects carrying mutations in NPHS1, NPHS2, WT1 (NPHS4), and ADCK4 (NPHS9) as non-RCAD." (PMID 30778115, 2019). "Mutations in the nephrin encoding gene NPHS1 or lack of NEPH1 lead to defective assembly of the foot processes and loss of the slit diaphragm which becomes evident as (congenital) nephrotic syndrome." (PMID 30057894, 2018).